BRD4 (bromodomain containing 4)
Diseases named in the same sentence as BRD4 in open-access papers (continued):
Sharing a sentence is not in itself a finding about the gene and the disease.
tumor (continued). "Interestingly, in a subset of genes such as MuRF1 and MAFbx/Atrogin-1, BRD4 also occupies regions of the gene body in muscles from C26-tumor-bearing mice, as previously reported for BRD4 targets in other experimental models." (PMID 29167426, 2017). "Interestingly, BRD4 can act in a tumor-promoting or tumor-protective manner depending on the type of tumors." (PMID 29296220, 2017). "However, it is predicted that the effects of these inhibitors would be restricted to tumours where c-MYC transcription is dependent on BRD4." (PMID 26729287, 2016). "Expression of BioTAP -tagged BRD4-NUT causes the formation of hyperacetylated nuclear foci in 293T cells that are similar in number and appearance to those of endogenous BRD4-NUT in cultured NMC cells and in NMC tumor tissues." (PMID 27827996, 2016). "Finally, JQ1, a BRD4 inhibitor combined with everolimus exhibited increased tumor growth inhibition in 3D Matrigel models and an in vivo xenograft model." (PMID 25537515, 2015). "Inhibition of BRD4 has been shown to have a positive effect on MYC-dependent tumor cells." (PMID 24840099, 2014). "BRD4, a target of BET inhibitors, encodes two isoforms with opposite effects on tumor progression." (PMID 24260471, 2013). "Additionally, the Brd4 long- and short-isoform gene expression signatures were compared to a 19-gene signature that was defined by correlating tumor growth expression, histological grade, and survival." (PMID 22295248, 2012). "Finally, in multiple tumor models, BRD4 inhibition improved the efficacy of anti–PD-L1 therapy." (PMID 40762981, 2025). "Notably, combining SMYD5 knockdown with BRD4 inhibition using (+)-JQ1 enhances anti-tumor effects significantly, indicating a synergistic interaction that could be exploited for therapeutic benefit." (PMID 40872497, 2025). "Nanostring data from BRD4 inhibitor–treated tumors also revealed decreased tumor expression of chemokines important for MDSC recruitment to tumors including CXCL5, CXCL3, and CCL2, suggesting that the reduced intratumoral MDSC levels could be caused by impaired MDSC migration into the TME." (PMID 40762981, 2025). "Moreover, epigenetic reader BRD4 may directly bind to the promoter region of integrins or FAK in tumor cells, based on the ChIP‐qPCR analysis in two recent studies." (PMID 40959971, 2025). "Interestingly, while BRD4 has been classically associated with the promotion of epithelial-to-mesenchymal transition (EMT) and tumor invasion, our findings reveal a distinct role for BRD4 in maintaining E-cadherin expression and supporting epithelial features in PCa." (PMID 40407591, 2025). "NHWD-870 has many beneficial properties, including inhibition of tumor proliferation by inhibiting BRD4 and c-MYC transcription, inhibition of tumor-associated macrophages (TAM) development, and reduction of CSF-1 (colony-stimulating factor) secretion by tumor cells." (PMID 40650308, 2025). "Consequently, combined targeting of SMYD5 and BRD4 may enhance anti-tumor effects, reinforcing the potential for dual-targeted approaches." (PMID 40872497, 2025). "No BRD4::NUTM1 was expressed in NC surrounding normal epithelial or tumor-associated stromal cells." (PMID 38724194, 2024). "Similarly, BRD4 expression was elevated in 6 archival ERMS tumour sections." (PMID 38191874, 2024). "This study was undertaken to assess whether BRD4 controls IL-34 expression in IBD because there is evidence that both these proteins are up-regulated in the inflamed intestine of IBD patients, and studies in tumor cells have shown the ability of BRD4 to positively regulate IL-34 expression." (PMID 39451216, 2024). "Therefore, BRD4 inhibitors are expected to become a target for inhibiting tumor growth." (PMID 38565708, 2024). "Therefore, we first detected BRD4 protein expression in tumor tissues by Western blot." (PMID 39140036, 2024).
tumor (continued). "Highlighting the potential ‘yin-yang’ nature of alternative splicing, the short isoform of BRD4 (BRD4-S) generated from exon 12–20 skipping was oncogenic in breast cancer cell proliferation and metastasis, whereas the long isoform BRD4-L exhibited tumor suppressor properties." (PMID 38539439, 2024). "Moreover, the application of BRD4 inhibitors can enhance the anti-tumor effects of Dasatinib in GC." (PMID 39744132, 2024). "The similar tumor suppression and angiogenesis phenotypes and gene expression profiles between ASPSCR1::TFE3 loss and the JQ1 treatment suggests the critical role of SEs modulated by ASPSCR1::TFE3, although the mechanism by which Brd4-inhibition targets certain SEs awaits clarification." (PMID 37029109, 2023). "The role of LOXL2 and BRD4 in DNA damage and their cooperation in controlling the transcriptional regulation of cell cycle progression may suggest that their simultaneous inhibition in tumor cells could act as a double‐edged sword." (PMID 37937685, 2023). "However, whether BET/BRD4 inhibition will block LPS-promoted tumor metastasis in vivo remains to be tested." (PMID 37686037, 2023). "BRD4 inhibitor JQ1 may regress tumor growth by other mechanisms in addition to PD-L1 inhibition." (PMID 37328484, 2023). "In addition to CD180, chemokine receptor type 2 (CCR2) mRNA levels were downregulated in response to AZD5153 treatment, thus BRD4 inhibition may modulate the transmigration of tumor cells within the microenvironment." (PMID 37460961, 2023). "Therefore, long-term treatment with BRD4 inhibitors might promote multidrug resistance and tumor progression, and close monitoring and prompt intervention are required in clinical trials." (PMID 38135679, 2023). "Thus, ETV4 and ETV5 may act as key downstream effectors of BRD4 to promote tumor growth and dictate BETi efficacy." (PMID 36475791, 2022). "Therefore, we wonder whether BRD4 inhibition may boost anti‐tumour immunity and overcome resistance in vivo by suppressing chemoradiation‐induced PD‐L1 expression." (PMID 35083874, 2022). "Notably, miRNA mimics can simultaneously target several tumor-promoting genes, and BRD4 may be useful as a therapeutic target for tumor-suppressive miRNAs." (PMID 35204785, 2022). "However, since autophagy plays dual roles in tumor suppression and promotion, the possibility that Brd4 inhibition-induced autophagy could promote tumor growth should be considered." (PMID 36539410, 2022). "Some of the genes with the ability for comodulating the ECM-associated matrisome networks, like BRD4, are oncogenic but not tumor-suppressive in TNBC, implying that targeting the ECM or its network may be a viable method for disease treatment." (PMID 35911730, 2022). "The TCGA database also identifies that grade 1 HNSCC tumour had significantly lower BRD4 expression than the higher grades implicating that BRD4 is upregulated in higher grade tumours linking to their therapy resistance and that BRD4 could be a therapeutic target in HPV-positive HNSCC." (PMID 36333293, 2022). "In addition to known tumor-promoting genes, e.g., c-MYC, YAP1, RAD51B, TRIB3, SLC17A9, JADE1, we found that NAPRT, encoding a key enzyme for NAD+ biosynthesis from nicotinic acid, was also suppressed in HCC cells by the BRD4 inhibitor." (PMID 35399501, 2022). "Therefore, we next determined whether knockdown of BRD4 in MDA-MB-231 cells with shRNA inhibited tumor growth in vivo." (PMID 36499487, 2022). "In search of chromatin-activated neoplasia effectors, the authors observed a rapid increase in alarmin cytokine IL-33 as well as a swift and selective gain of IL-33 locus in KRAS-mutated epithelial cells undergoing injury-facilitated chromatin switch in a BRD4-dependent manner." (PMID 34023857, 2021).
tumor (continued). "In fact, Takagawa reported that hsa-miR-1293 was able to suppress in vivo tumor growth in a xenograft mouse model through the inhibition of BRD4 and DNA repair genes, and hypothesized that this miRNA could be a candidate for the development of miRNA-based therapeutics." (PMID 32498409, 2020). "Moreover, in‐depth mechanistic research showed that BRD4 was concentrated at the promoter region of Notch1 and may be involved in the process of tumor metabolism." (PMID 33135348, 2020). "BRD4 was enriched at Notch1 promoter region and may be involved in the process of tumor metabolism." (PMID 33135348, 2020). "Thus, this evidence suggests that telomere alterations in aggressive TCs may rely on BRD4 activity, prompting the use of BETi already employed in clinical trials for several tumor settings." (PMID 31200515, 2019). "Although it is well accepted that BRD4-guided gene expression mediates diverse processes during tumor development and progression, whether and how BRD4 assembles transcriptional machinery on chromatin to activate feedback survival genes expression is totally unclear." (PMID 30518851, 2018). "In addition, in vivo tumor growth was reduced by BRD4 inhibition in a xenograft mouse model." (PMID 29312470, 2018). "Interestingly, BRD4 has also been found to have tumor-promoting activity in these cancers." (PMID 29434197, 2018). "However, it remains unclear whether BRD4-mediated gene transcription is required for tumor cells to develop drug resistance." (PMID 30518851, 2018). "Thus, it remains unclear whether Brd4 is indeed the protein that mediates the anti-tumor effects of BET inhibitors." (PMID 28490802, 2017). "As a PROTAC molecule capable of targeting the BRD4 protein in TNBC, dBET6 exhibits anti-tumor properties and holds promise for overcoming resistance to traditional chemotherapy drugs in TNBC." (PMID 41525248, 2026). "We performed immunoblotting on the tumor tissues harvested from the animal experiment to assess the expression of MYCN, BRD4, and their respective phosphorylation along with H3K27 acetylation." (PMID 41539997, 2026). "Next, we investigated the BRD4 degrading efficiency of Alb-TAC in a cell culture system and in CT26 tumor-bearing mice." (PMID 42094600, 2026). "Given the high expression of BRD4 in TNBC and its correlation with tumor malignancy and prognosis, BRD4 degraders have been extensively investigated for the treatment of TNBC." (PMID 41525248, 2026). "In vitro, Gip significantly improved cellular uptake in 4T1 cells and 3D tumor spheroids via GLUT1-mediated transport, leading to more efficient BRD4 degradation and greater cytotoxicity than lip." (PMID 41567737, 2026). "We constructed a multifunctional theranostic nanoplatform (PCN-CuS-JQ/RGD) based on an MRI-visible, Fe-porphyrin MOF (PCN(Fe)) carrier, decorated with CuS photothermal agents, a BRD4 inhibitor (JQ1), and a tumor-targeting peptide (RGD)." (PMID 41662485, 2026). "Preclinical studies have shown that the BRD4 inhibitor I-BET762 (GSK525762A) effectively eliminates common B-ALL cells and suppresses tumor cell proliferation." (PMID 40454861, 2025). "Bromodomain-containing protein 4 (BRD4), a key epigenetic regulator in TNBC, drives oncogene transcription and promotes tumor cell survival; however, the application of its inhibitor JQ1 is often limited by drug resistance." (PMID 41471274, 2025). "While this study suggests that BRD4 inhibition acts predominantly by reducing MDSC abundance and recruitment to the tumor, other work has shown that BRD4 inhibition can alter immune macrophage phenotypes." (PMID 40762981, 2025). "JQ1, a prototypical BET inhibitor, was the first-in-class compound developed to disrupt BRD4-chromatin interactions, leading to MYC downregulation and tumor growth inhibition." (PMID 41335282, 2025).
tumor (continued). "When paired with an immune checkpoint blockade in vivo, BRD4 inhibitors significantly improved the efficacy of anti–PD-L1 and anti–LAG-3 therapy, resulting in overall reduced tumor growth and improved survival." (PMID 40762981, 2025). "Specifically, BRD4, FLT3, and SIAH2 were upregulated in tumor tissues, whereas CS and PIK3CA were downregulated." (PMID 40696656, 2025). "Prostate cancer studies revealed that LSD1, along with BRD4 and FOXA1, formed a network enriched in the super enhancer region to regulate MYC expression and influence tumor development." (PMID 39838405, 2025). "For instance, the expression of writers such as EHMT2, readers such as BRD4, or erasers such as HDAC5 is high in tumor tissues." (PMID 39774014, 2025). "Innovative strategies, such as JQ1-loaded nanoplatforms with improved tumor targeting and OPT-0139, a dual BRD4/nitric oxide donors, further enhance therapeutic efficacy." (PMID 41583469, 2025). "Last, we found that P-selectin–targeted nanoPROTACs encapsulating degraders of BRD4 and MEK1/2 led to enhanced tumor localization over normal tissue, efficient target degradation, and significantly improved antitumor efficacy in murine solid tumor models." (PMID 41348877, 2025). "Our functional analysis reveals a strong dependence of a fraction of CRC tumor cell lines on the integrin‐FAK pathway and its crosstalk with YAP1 and the BRD4‐MYC axis." (PMID 40959971, 2025). "By utilizing the unique characteristics of the tumor microenvironment, this region-confined PROTAC system enhanced the degradation of BRD4 and amplified the antitumor efficacy of ARV-771, which is activated by the stimuli-responsive system within tumor cells." (PMID 40284496, 2025). "Recent studies have highlighted that signaling pathways such as BRD4/IRF1, PI3K/AKT, and FAK/Src contribute to PD-L1 upregulation, facilitating tumor immune escape." (PMID 40735646, 2025). "When comparing the tumor tissues and the normal tissues, the expression of BRD4, EMC2, FLT3, and SIAH2 was upregulated in the tumor tissues." (PMID 40696656, 2025). "In NSCLC, inhibition of BRD4 enhances tumor necrosis factor-related apoptosis-inducing ligand (TRAIL)-induced apoptosis and restrains tumor growth by downregulating eukaryotic translation initiation factor 4E (eIF4E)." (PMID 41184230, 2025). "Inhibition of the mSW/SNF complex, which specifically targets SMARCA4/2 ATPases and BRD4, has been shown to impede SCLC-P tumor growth." (PMID 41194225, 2025). "The compound (+)-JQ1, known as a potent and selective inhibitor of BRD4, interferes with BET protein binding to acetylated lysines on histones and transcription factors, thus suppressing tumor growth." (PMID 40872497, 2025). "Individual constituents of super enhancers, such as BRD4, CDK7, or CDK9, have demonstrated significant potential in multiple preclinical tumor models." (PMID 39838405, 2025). "Targeting BRD4-mediated YAP1 expression in MEK-resistant melanomas also potentiates trametinib therapy, producing strong anti-tumor synergy." (PMID 41583469, 2025). "Together, these results suggested that inhibiting BRD4 with JQ1 disturbed cell cycle progression, enhancing the anti-tumor effects of RSL3 in tumor xenografts in mice." (PMID 41249136, 2025). "Specifically, BRD4 was shown to maintain the active form of NF-κB in tumors, while BET inhibition broadly sensitized diverse tumor cell lines to the cytotoxic activity of TNF, involving the suppression of pro-survival NF-κB transcription." (PMID 40858106, 2025). "DNA methyltransferases (DNMTs), histone deacetylases (HDACs), EZH2, bromodomain protein 4 (BRD4), and lysine-specific histone demethylase 1A (LSD1), which play important roles in tumor biology, have also been shown to regulate anti-tumor immunity as well." (PMID 38275900, 2024). "Among BRD4 targets, we also identified CEACAM1, which was reported to inhibit NK-mediated cytolysis of tumor cells and KLRG1, a negative regulator of CD8+ lymphocytes and NK cells." (PMID 38519469, 2024).
tumor (continued). "Parallel IHC with a specific antibody for BRD4, a well-known SPOP substrate, displayed similar increased patterns in tumor tissues." (PMID 38632244, 2024). "The results demonstrated that when NIR light was applied to tumor tissues containing NGP-63 nanocages, BRD4 degradation occurred, leading to significant suppression of tumor growth." (PMID 38773495, 2024). "Other tumour growth-related genes, such as Myb, KRAS, Akt-3, and CDK4 were also downregulated by the three BRD4 inhibitors in PDAC cells." (PMID 38279262, 2024). "We report on a series of cases that show fusions involving BRD4 and LEUTX and match to the corresponding DKFZ-Heidelberg class describing this tumor type." (PMID 38500181, 2024). "Several small molecules have been designed to bind and inactivate BRD4, including JQ1 and I-BET-762, and are effective in reducing tumor growth and inflammation." (PMID 39337472, 2024). "Presently, several BRD4 degraders have been created for GBM treatment and have exhibited substantial anti-tumor impacts in GBM models, including GNE987, dBET6, ZBC260, and ARV-825." (PMID 38365636, 2024). "As the BRD4 inhibitor, JQ1 can reduce the expression of MYCN and inhibit tumor growth in MYCN-amplified NB, but its effect seems unsatisfactory when used alone." (PMID 38336749, 2024). "The inhibitors block the binding of BRD4 proteins to acetylated histones, resulting in the downregulation of several oncogenes in PDAC cells and direct inhibition of tumour growth." (PMID 38279262, 2024). "Administration of dBET1 reduced tumor progression in murine xenograft model of human AML cells, accompanied by degradation of BRD4 and downregulation of c‐Myc." (PMID 38845697, 2024). "In all 3 cases, expression of BRD4, and especially that of LEUTX was high relative to expression of these genes in the broad dataset of tumor types." (PMID 38500181, 2024). "Numerous BET inhibitors, particularly the BRD4 inhibitor JQ1, have demonstrated the ability to downregulate MYC and impede tumor growth in various animal models with MYC activation." (PMID 38383388, 2024). "Broadly suppressing effects of histone acetylation by targeting the epigenetic reader BRD4 with the small-molecule inhibitor JQ1 repressed angiogenesis-related gene expression and inhibited ex vivo tumor formation." (PMID 38916046, 2024). "The results indicated that the expression levels of BRD2, BRD3, BRD4 were higher in GBM tumor tissues than those in normal tissues, and BRDT expression in tumor was lower than that in normal tissues." (PMID 36711038, 2023). "Besides directly suppressing tumor growth via the inhibition of Brd4 and c-MYC transcription, NHWD-870 also suppressed the proliferation of tumor-associated macrophages (TAMs) through reducing the expression and secretion of the macrophage colony stimulating factor CSF1 by tumor cells." (PMID 37049806, 2023). "The overexpression of BRD4, at both genomic and protein levels, has been reported in HGSOC cells, resulting in a more aggressive tumor phenotype and poor prognosis." (PMID 38201534, 2023). "JQ1 releases BRD4 from chromatin and reduces MYC transcription and tumor growth in endometrial and ovarian cancers." (PMID 36969025, 2023). "MYC gene expression is tightly regulated by PI3K and BRD4, therefore concomitant inhibition of PI3K and BRD4 blocks MYC expression and activation, leading to decreased tumor growth and metastasis." (PMID 37142850, 2023). "A very recent study in AML reported a highly promising PROTAC compound MZ1, which targets and efficiently degrades BRD2, BRD3, and BRD4 proteins in various AML cell lines, and markedly suppress tumor growth in a xenograft mouse model." (PMID 36909156, 2023). "The same group also reported the induction of BRD4 by LPS in the RAW264.7 macrophage cell line and the BEAS-2B bronchial epithelial cell line as well as in an LPS-promoted tumor metastatic model." (PMID 37686037, 2023).